TCF7L1 (transcription factor 7 like 1)
Description:
Participates in the Wnt signaling pathway. Binds to DNA and acts as a repressor in the absence of CTNNB1, and as an activator in its presence. Necessary for the terminal differentiation of epidermal cells, the formation of keratohyalin granules and the development of the barrier function of the epidermis (By similarity). Down-regulates NQO1, leading to increased mitomycin c resistance.
Synonyms: formerly TCF3
Tractability: PROTAC: ubiquitination databases record sites on it.
Gene: Protein-coding gene on chromosome 2 (85,133,392 to 85,310,388, forward strand). Ensembl gene ENSG00000152284.
Subcellular location: Nucleus
Subcellular location (Human Protein Atlas): Nucleoplasm; Cytosol
Pathways (Reactome):
Signal Transduction: Binding of TCF/LEF:CTNNB1 to target gene promoters; Ca2+ pathway; Deactivation of the beta-catenin transactivating complex; Formation of the beta-catenin:TCF transactivating complex; Repression of WNT target genes
Developmental Biology: Regulation of MITF-M-dependent genes involved in cell cycle and proliferation; Specification of the neural plate border
Gene expression (Transcription): RUNX3 regulates WNT signaling
Immune System: Regulation of PD-L1(CD274) transcription
Gene Ontology:
Molecular function: protein binding; sequence-specific double-stranded DNA binding; DNA binding; DNA-binding transcription factor activity; DNA-binding transcription factor activity, RNA polymerase II-specific; RNA polymerase II cis-regulatory region sequence-specific DNA binding
Biological process: canonical Wnt signaling pathway; chromatin organization; regulation of DNA-templated transcription; regulation of transcription by RNA polymerase II; regulation of Wnt signaling pathway; Wnt signaling pathway
Cellular component: nucleoplasm; beta-catenin-TCF complex; chromatin; nucleus
Genetic constraint (gnomAD): Loss-of-function variants: 18 observed, 56.57 expected, observed/expected ratio (o/e) 0.32, 90% interval 0.22 to 0.47. The upper end of that interval is the gene's LOEUF score, 0.47, which puts it in group 2 of 6, group 1 being the genes least tolerant of losing a copy. Missense variants: 643 observed, 729.98 expected, observed/expected ratio (o/e) 0.88, 90% interval 0.82 to 0.94. Synonymous variants: 345 observed, 320.02 expected, observed/expected ratio (o/e) 1.08, 90% interval 0.99 to 1.18.
Homologues: Orthologues: chimpanzee TCF7L1 (99% identical), macaque TCF7L1 (99% identical), dog TCF7L1 (98% identical), mouse Tcf7l1 (96% identical), rat Tcf7l1 (96% identical), guinea pig TCF7L1 (95% identical), rabbit TCF7L1 (86% identical), tropical clawed frog tcf7l1 (75% identical), zebrafish tcf7l1a (71% identical), zebrafish tcf7l1b (70% identical). Paralogues in human: TCF7L2 (61% identical), LEF1 (38% identical), TCF7 (30% identical).
Diseases named in the same sentence as TCF7L1 in open-access papers:
TCF7L1 is named in the same sentence as 55 diseases in open-access papers, as found by Europe PMC text mining. Sharing a sentence is not in itself a finding about the gene and the disease. The quoted sentences say what the papers report.
breast carcinoma (13 papers, 2016 to 2025). "However, the mechanism underlying TCF7L1’s tumor-promoting role in breast cancer remains to be defined." (PMID 28467300, 2017). "Previous studies have shown that TCF7L1 decreases upon Wnt activation in prominent embryonic stem cells (ESCs) and poorly differentiated breast cancer." (PMID 37957244, 2023). "In the poorly differentiated breast cancer cell line, 4T1, which prominently expresses TCF7L1, a cycloheximide assay was performed, which confirmed that the overexpression of RNF2 decreased the stability of TCF7L1." (PMID 37957244, 2023). "Studies have shown that ectopic TCF7L1 expression impairs the growth and invasion of highly metastatic breast cancer cells." (PMID 36105798, 2022). "It was found that in breast cancer and colorectal cancer, the elimination of TCF7L1 expression reduced tumor cell progression and metastasis." (PMID 34070502, 2021). "TCF7L1 is involved in the occurrence and progression of many human tumors such as endometrial cancer, breast cancer, and gastric cancer." (PMID 33824876, 2021). "T-cell factor 7-like 1 (TCF7L1) has been found to have a high expression in many cancers, such as breast cancer and skin squamous cell carcinoma." (PMID 34603375, 2021). "In breast cancer, for example, higher expression of TCF7L1 indicates worse prognosis, and silencing of TCF7L1 expression decreases tumor growth and metastasis." (PMID 30811526, 2019). "The implications of TCF7L1 in breast cancer and colorectal cancer have been attributed to its regulatory roles in the Wnt/β-catenin pathway." (PMID 30811526, 2019). "TCF7L1 is an embryonic stem cell signature gene that is upregulated in multiple aggressive cancer types, including breast cancer, glioblastoma, and bladder carcinoma." (PMID 28467300, 2017). "In a xenograft model of breast cancer, downregulation of TCF7L1 decreased tumor growth and reduced metastasis rate." (PMID 28467300, 2017). "In human breast cancer, high levels of TCF7L1 are found in high-grade tumors and its expression is associated with poor survival." (PMID 28467300, 2017). "Specifically, it is necessary to examine the regulatory role of RNF2 in TCF7L1-mediated breast cancer metastasis, as well as to explore whether RNF2-mediated regulation of TCF7L1 occurs only at the cellular level or requires other components." (PMID 37957244, 2023). "In breast cancer and colorectal cancer, TCF7L1 regulates Wnt/β-catenin signaling." (PMID 34070502, 2021). "TCF7L1 has been shown to promote tumor growth in both xenograft models of human breast cancer and colorectal cancer, but it is not clear whether TCF7L1 functions as an activator or repressor to exert its tumorigenic role." (PMID 28467300, 2017). "As a TCF/LEF protein belonging to the HMG box family, TCF7L1 is a major downstream effector of the Wnt signaling pathway and is an embryonic stem cell signature gene whose expression is upregulated in multiple aggressive cancer types, including breast cancer, glioblastoma, and bladder cancer." (PMID 38370338, 2024). "However, a study in breast cancer cells showed that TCF7L1 knockdown led to the simultaneous upregulation and downregulation of different subsets of WNT target genes, suggesting that TCF7L1 may directly or indirectly play an activating role in WNT signaling." (PMID 28467300, 2017). "Therefore, although that TCF7L1 may function as an activator and repressor in breast cancer cells, its tumorigenic role may depend only on its function as a repressor." (PMID 28467300, 2017). "Our independent analysis of primary ER+PIK3CA-mutant breast cancers, which exhibit high INPP4B expression, identified these and additional upregulated Wnt genes (LEF1, MYCN, FZD7, SFRP2, TCF7L1, CTNNB1, FZD4, and SFRP1)." (PMID 34035258, 2021). "In breast cancer cell line MDA-MB-468, overexpression of TCF7L1 together with β-catenin increased TOP-FLASH activity, suggesting that it functions as a coactivator with β-catenin." (PMID 28467300, 2017).
breast carcinoma (continued). "We also examined the expression of these genes in a separate cohort of 698 luminal (ER/PR+) breast cancers using the TCGA dataset, where PIK3CA-mutant cancers displayed significantly higher expression of eight Wnt genes (LEF1, TCF7L1, TCF7L2, CTNNB1, LRP6, SFRP2, WNT5A, and MSX2)." (PMID 34035258, 2021). "We observed the downregulation of the Wnt pathway ligand Wnt-3A and the Wnt-dependent transcription factor TCF7L1 in Sdc-1-depleted MCF-7 cells, which is in accordance with our previous observation of a downregulation of the Wnt-coreceptor LRP6 in Sdc-1-depleted breast cancer cells." (PMID 34070901, 2021). "Moreover, since downregulation of TCF7L1 in breast cancer cells decreased the expression of some WNT-responsive genes while increasing a different subset, it implies that TCF7L1 can act as an activator or repressor depending on the targets." (PMID 28467300, 2017).
colorectal cancer (8 papers, 2016 to 2024). A primary or metastatic malignant neoplasm that affects the colon or rectum. "Moreover, the related ephrinB3 (EPHB3), a Paneth cell marker and tumor suppressor, has recently been linked in cell line models of human colorectal cancer to transcriptional suppression specifically by TCF7L1." (PMID 32403323, 2020). "First, we and others have found abundant expression of TCF7L1 proteins in established human colorectal cancer cell lines indicating that despite lower levels of transcripts, functional protein is expressed." (PMID 36833408, 2023). "TCF7L1 has been shown to regulate tumor growth in many types of cancers, such as leukemia and colorectal cancer." (PMID 30811526, 2019). "In colorectal cancer, TCF7L1 positively regulates cell proliferation, and silencing its expression reduces the size of xenografted tumors." (PMID 30811526, 2019). "In light of these observations, we wanted to investigate the specific function of TCF7L1 in colorectal cancer models to determine how it regulates cell proliferation, tumor growth, and CTNNB1/TCF target gene expression." (PMID 27333864, 2016). "However, previous analyses of transcriptome data indicate that TCF7L1 transcripts are downregulated in human colorectal cancers versus normal colonic control tissues." (PMID 36833408, 2023). "In colorectal cancer, high level of TCF7L1 mRNA also correlates with shorter survival of patients." (PMID 28467300, 2017). "We found that rs11954856 in the APC gene was associated with colorectal cancer and could increase the expression levels of APC, β-catenin, TCF7L1, TCF7L2 and LEF1 genes in the pathway in the CRC patients, demonstrating the involvement of APC in the pathological processes leading to CRC." (PMID 29050326, 2017). "For example, TCF7L1 has been reported to recruit CtBP and HDAC1 to epigenetically repress tumor-suppressor DICKKOPF4 gene in colorectal cancer cells." (PMID 30811526, 2019). "In colorectal cancer cell line HCT116, downregulation of TCF7L1 increased WNT reporter TOP-FLASH activity in vitro, suggesting that TCF7L1 functions as a repressor." (PMID 28467300, 2017). "Pathways affected in TCF7L1-cells include ECM-receptor interaction, adhesion, and genes involved in colorectal cancer." (PMID 27333864, 2016). "Roles for LEF/TCF proteins has been studied in tissue-culture and animal models of intestinal stem cells and colorectal cancer, which suggested roles for TCF7L2 and TCF7 in normal colorectal tissue, where LEF1 and TCF7L1 are silent, but strong expression in colorectal tumor of LEF1 and TCF7." (PMID 32403323, 2020). "Together, these findings indicate that activation of EPHB3 is at least partially responsible for reduced HCT116 colorectal cancer cell growth observed in the absence of TCF7L1." (PMID 27333864, 2016). "In our meta-analysis, NFE2L2 is noticeable for the large discrepancy between positive correlation with LEF1 and negative correlation with TCF7L1, which clearly substantiates the importance of NFE2L2 as an important WNT/β-catenin target gene in human colorectal cancer." (PMID 32403323, 2020). "However, in HCT116 colorectal cancer cells, knockdown of CTNNB1 did not increase TCF7L1 protein levels, and CTNNB1 stabilization by addition of Wnt3a showed only a modest decrease in TCF7L1 protein." (PMID 27333864, 2016).
prostate carcinoma (6 papers, 2021 to 2026). A carcinoma that arises from epithelial cells of the prostate gland. "WNT4 located in 1p36 and the induction of WNT4/TCF7L1 resulted in increased malignancy in prostate cancer that was linked to dysregulation of androgen receptor signalling and activation of the IL‐8/CXCR2 pathway." (PMID 37378426, 2023). "Study findings of predicted target genes regulated by miR-185-3p indicated that TCF7L1 is highly expressed in prostate cancer, skin squamous cell carcinoma and gastric cancer and is related to their occurrence and progression." (PMID 36271413, 2022). "ADT induced the secretion of WNT4 which upon engagement of TCF7L1 in prostate cancer cells, enhanced IL-8 and CXCR2 expressions." (PMID 34799554, 2021). "Our results suggest that induction of WNT4/TCF7L1 results in increased NED and malignancy in prostate cancer that is linked to dysregulation of androgen receptor signaling and activation of the IL-8/CXCR2 pathway." (PMID 34799554, 2021). "In this study, we identified ADT-mediated upregulation of transcription factor 7 like 1 (TCF7L1), which increases the cytokine response and enhances NED of prostate cancer through interleukin (IL)-8/C-X-C motif chemokine receptor type 2 (CXCR2) signaling activation." (PMID 34799554, 2021).
bladder cancer (4 papers, 2017 to 2024). "Exploring the transcriptional regulation of HSPB6, our investigation extended to the expression of TCF7L1 within bladder cancer tissues." (PMID 39608715, 2024). "Rescue experiments showed that after overexpression of TCF7L1 and knocking down HSPB6, the expression of these proteins was reversed, indicating that TCF7L1 targeting HSPB6 is involved in the pathological process of EMT in bladder cancer." (PMID 39608715, 2024). "From these results, it becomes evident that HSPB6 knockdown significantly counteracts the growth-inhibitory and anti-migratory effects imparted by TCF7L1 overexpression in bladder cancer cells." (PMID 39608715, 2024). "This emphasizes the crucial function of HSPB6 in facilitating the inhibitory effect of TCF7L1 on the progression of BLCA cells, shedding light on the complexities of their regulatory interaction within the cellular environment of bladder cancer." (PMID 39608715, 2024).
colon cancer (4 papers, 2011 to 2022). "Knockdown of VBP1 also decreased TCF7L1 and TCF7L2 protein levels in Wnt-activated HCT116 colon cancer cells, which harbor an oncogenic mutation in β-catenin." (PMID 32989053, 2020). "Positive autoregulation has been described before for LEF1 in colon cancer, XTcf-4 (Tcf7l2) in Xenopus midbrain and zebrafish Tcf3 (Tcf7l1)." (PMID 29942461, 2018). "The family member TCF7L1 is however also expressed in the colon crypt and in colon cancer." (PMID 21853123, 2011).
psoriasis (3 papers, 2016 to 2023). An autoimmune condition characterized by red, well-delineated plaques with silvery scales that are usually on the extensor surfaces and scalp. "LCN2 is highly expressed in the skin lesions and the serum of patients with psoriasis and can inhibit the synthesis of keratin, involucrin, and loricrin in KCs, leading to epidermal parakeratosis via the Tcf7L1-lipocalin 2 signaling axis." (PMID 36950008, 2023).
skin squamous cell carcinoma (3 papers, 2017 to 2022). A carcinoma arising from the squamous cells of the epidermis. "Here we document TCF7L1 upregulation in skin squamous cell carcinoma (SCC) and demonstrate that TCF7L1 overexpression increases tumor incidence, tumor multiplicity, and malignant progression in the chemically induced mouse model of skin SCC." (PMID 28467300, 2017).
acute lymphoblastic leukemia (2 papers, 2015 to 2024). Leukemia with an acute onset, characterized by the presence of lymphoblasts in the bone marrow and the peripheral blood. "BCR-ABL-positive acute lymphoblastic leukemia with high TCF7L1 expression is associated with poor prognosis, and TCF7L1 knockdown significantly reduces cell proliferation and colony formation." (PMID 38370338, 2024).
colorectal adenocarcinoma (2 papers, 2021 to 2023). The most common type of colorectal carcinoma. "The cBioPortal database was used to analyze the mutations of seven genes, which showed that E2F3, ETS2, HLF, HSF4, KLF4, MEIS2, and TCF7L1 were altered in 8, 8, 6, 6, 5, 9, and 6% of 524 colorectal adenocarcinoma patients separately." (PMID 34603375, 2021). "To begin to test this hypothesis, we first determined whether there was an association between TCF7L1 and LGR5 expression in tumor and normal colonic tissue samples available in the colorectal adenocarcinoma (COAD) data set within The Cancer Genome Atlas (TCGA) database." (PMID 36833408, 2023).
osteosarcoma (2 papers, 2024). A usually aggressive malignant bone-forming mesenchymal neoplasm, predominantly affecting adolescents and young adults. "Summarizing these results, it can be inferred that miR-329-3p exerts anticancer effects in osteosarcoma by inhibiting TCF7L1." (PMID 38370338, 2024). "This study sought to elucidate the impact of the interaction between miR-329-3p and TCF7L1 on the growth and apoptosis of OS and analyze the regulatory expression relationship between miRNA and mRNA in osteosarcoma cells using a variety of approaches." (PMID 38370338, 2024). "Osteosarcoma cell cycle arrest and pathway inhibition were observed upon the regulation of TCF7L1 by miR-329-3p." (PMID 38370338, 2024). "Compared to human mesenchymal stem cells (hMSCs), osteosarcoma cells express significantly less miR-329-3p and more TCF7L1." (PMID 38370338, 2024).
abdominal aortic aneurysm (1 paper, 2024). Enlargement and ballooning of the vessel that supplies arterial blood to the abdomen, pelvis and legs. "Recent studies have shown that TCF7L1 (transcription factor 7-like 1) reduces the transcriptional activity of SRF and promotes the phenotypic transformation of VSMC, which aggravates the formation of abdominal aortic aneurysm." (PMID 38913045, 2024).
Anxiety (1 paper, 2020). Intense feelings of nervousness, tension, or panic often arise in response to interpersonal stresses. "SUZ12, TCF7L1, and BCL3 could bind to the CNR1 promoter region to regulate the expression of CNR1, which was associated with anxiety and chronic pain." (PMID 32434423, 2020).
autism spectrum disorder (1 paper, 2023). A spectrum of developmental disorders that includes autism, and Asperger syndrome. "The association of many differentially expressed genes to TCF7L1 is supported by a meta-analysis of transcriptome experiments that associated this transcription factor with autism spectrum disorder." (PMID 37851674, 2023).
cervical cancer (1 paper, 2021). A primary or metastatic malignant neoplasm involving the cervix. "First, we determined the impact of TCF7L1 genetic variants on cervical cancer risk; the molecular mechanism of genetic variants on cervical cancer will be conducted in the future." (PMID 33824876, 2021). "The correlation between TCF7L1 variants and cervical cancer risk was examined by the multiple genetic models with adjustment for age." (PMID 33824876, 2021). "Our study showed that rs11904127 (OR 0.79, p = 0.010) and rs62162674 (OR 0.82, p = 0.044) of TCF7L1 significantly decreased cervical cancer risk." (PMID 33824876, 2021). "In this study, we firstly detected the impact of TCF7L1 SNPs on cervical cancer risk in a Chinese population." (PMID 33824876, 2021). "TCF7L1 genetic variants may relate to cervical cancer progression according to the impact of the gene expression level." (PMID 33824876, 2021). "The rs11904127 of TCF7L1 significantly decreased cervical cancer risk under allele model (A vs. G, OR 0.79, p = 0.010), codominant model (GA vs. GG, OR 0.68, p = 0.006; AA vs. GG, OR 0.67, p = 0.043), dominant model (GA-AA vs. GG, OR 0.68, p = 0.003), and Log-additive model (OR 0.79, p = 0.010)." (PMID 33824876, 2021). "Our study found that TCF7L1 variations have a protective effect on cervical cancer risk." (PMID 33824876, 2021). "Recent evidence indicated that abnormal expression of the TCF7L1 gene contributed to the occurrence of cervical cancer by regulating tumor behaviors including cell growth, invasion, and migration." (PMID 33824876, 2021). "Nowadays, increasing studies revealed that TCF7L1 is an essential factor in the occurrence and progression of cervical cancer." (PMID 33824876, 2021). "We then explored the relationship between TCF7L1 variations and cervical cancer in a Chinese population." (PMID 33824876, 2021). "Another study also indicated that the downregulation of TCF7L1 has an obvious antitumor effect on cervical cancer." (PMID 33824876, 2021). "Rs11904127 and rs62162674 in TCF7L1 are related to cervical cancer." (PMID 33824876, 2021).